MMP9 (matrix metallopeptidase 9)
Diseases named in the same sentence as MMP9 in open-access papers (continued):
Sharing a sentence is not in itself a finding about the gene and the disease.
gingivitis (17 papers, 2013 to 2026). A disorder involving inflammation of the gums; may affect surrounding and supporting structures of the teeth. "MMP-9 is one of the major gelatinase-degrading enzymes, which is mainly responsible for degradation of matrix proteins in inflamed tissue during gingivitis and adult periodontitis." (PMID 33735248, 2021). "In our study, change of MMP-8 and MMP-9 in saliva were measured to confirm improvement of gingivitis." (PMID 34679720, 2021). "Women with PCOS and gingivitis had significantly higher MMP-9 than all groups." (PMID 36874743, 2023). "Similarly, no significant phylogenetic similarity was found between samples when grouped by the net changes in proinflammatory cytokine interleukin-8 (IL-8), MMP-8, or MMP-9 between day 1 and day 21 of the experimental gingivitis study." (PMID 29666288, 2018). "Grant and colleagues revealed that a combination of MMP9, alpha-1-acid glycoprotein (A1AGP), and pyruvate kinase (PK) demonstrated notable diagnostic accuracy with an AUC of 0.954 in differentiating CP patients from healthy individuals or those with gingivitis." (PMID 37834046, 2023). "Although all the results of the MMP-9 in all groups are within the normal reference ranges, yet women with PCOS and gingivitis had significantly higher ranges than other groups." (PMID 36874743, 2023). "For discriminating health vs gingivitis groups, the predictor variables resulting from the CART analysis included MMP-9, TIMP-1." (PMID 33742017, 2021). "Women with PCOS but no gingivitis had significantly higher MMP-9 than women who had neither PCOS nor gingivitis." (PMID 36874743, 2023). "When MMP-9 levels were higher than 150.3 ng/ml, no further splits were made and this biomarker, alone, can classify patients with gingivitis with an accuracy of 90.5%." (PMID 33742017, 2021). "Previous studies have shown increased MPO levels in the GCF of patients with PCOS compared with healthy young women, while women with both PCOS and gingivitis were reported to exhibit significantly higher serum levels of MPO and MMP-9 than otherwise systematically healthy women with gingivitis." (PMID 32456146, 2020). "Blood and saliva are valid sources for the estimation of many biomarkers like MMP-9, and there is evidence that serum and salivary MMP-9 show significantly increased levels in women with PCOS and gingivitis, which may indicate an exaggerated effect of the gingival inflammatory process in PCOS." (PMID 36874743, 2023).
medulloblastoma (17 papers, 2010 to 2025). A malignant, invasive embryonal neoplasm arising from the cerebellum. "We next determined expression of MMP9 associated with meninges from 15 patients who underwent resection of medulloblastoma." (PMID 27255663, 2016). "Apoptosis in medulloblastoma, associated with loss of gelatinase B/MMP-9 expression, involves β1 integrin, ERK signalling and NF-κB activation." (PMID 24473089, 2014). "To identify the molecular events underlying the induction of apoptosis in uPAR and MMP-9 knockdown medulloblastoma cells, we initially focused on expression pattern of Bcl-2 family members." (PMID 22984561, 2012). "In addition to these medulloblastoma markers, we also assessed the expression of the matrix metalloprotease MMP9, which inactivates PN-1 and has been implicated in growth and malignant progression of different types of tumors including medulloblastomas (see Discussion)." (PMID 25901736, 2015). "Folr1 expression was up-regulated in medulloblastoma and positively correlated with percentage of Ki-67 and MMP9 labeling, pathological subtypes, serum Folr1 levels and CSF spreading on MRI." (PMID 28416738, 2017). "Conversely, pharmacological targeting of β-adrenergic functions abrogates MMP9 secretion in medulloblastoma cells suggesting a potential cross-talk between β-adrenergic receptors and MMP9." (PMID 27014091, 2016). "These lack Atoh1 expression and MMP9 is reduced in comparison to Ptch1Δ/+ medulloblastomas, while the expression of some differentiation markers is increased." (PMID 25901736, 2015). "MMP9 proteins are detected in PNLs of both genotypes and persist in medulloblastomas, while expression appears much reduced in cerebellar nodules." (PMID 25901736, 2015). "Recently, it has been shown that MMP9 is part of a regulatory feedback loop that functions in irradiation-induced angiogenesis in medulloblastoma cells." (PMID 25901736, 2015). "Our results showed that silencing uPAR and MMP-9 in the medulloblastoma cells significantly inhibited the activation (phosphorylation) of EGFR." (PMID 22984561, 2012). "In the present study, we demonstrate that nuclear levels of the phosphorylated Rel-A (the p65 subunit of the NF-κB complex) and NF-κB DNA binding activity was significantly inhibited in uPAR and MMP-9-silenced medulloblastoma cells." (PMID 22984561, 2012). "In an independent experiment we attempted to confirm that uPAR and MMP-9 induces the transactivation of EGFR in medulloblastoma cells lines." (PMID 22984561, 2012). "Radiation is one of the foremost methods applied for treating cancer and considerable evidence showed that radiation elevated uPAR and MMP-9 expression in medulloblastoma cell." (PMID 22984561, 2012). "Results from our studies suggest that apoptotic stimuli generated by downregulation of uPAR and MMP-9 counteract the function of anti-apoptotic Bcl-2 and Bcl-xL molecules and activate pro-apoptotic Bak in medulloblastoma cells." (PMID 22984561, 2012). "Even in the present study, we determined that the knockdown of uPAR and MMP-9 reduced the expression of total EGFR in medulloblastoma." (PMID 22984561, 2012). "Our results confirm that uPAR and MMP-9 regulate EGFR/STAT3 regulated signalling pathway in medulloblastoma." (PMID 22984561, 2012). "Transfecting medulloblastoma cells with pU, pM and pUM plasmids significantly inhibited uPAR and MMP-9 protein levels." (PMID 22984561, 2012). "Subsequently our antibody blocking experiment confirmed that blocking EGFR inhibited the activation of uPAR/MMP-9 induced STAT3 in medulloblastoma cell lines." (PMID 22984561, 2012). "Reduction in the cell number of pU, pM and pUM transfected cells made us to investigate the effect of uPAR and MMP-9 downregulation on medulloblastoma cells progression." (PMID 22984561, 2012). "We further confirmed the apoptosis induced by uPAR and MMP-9 downregulation in medulloblastoma by Annexin V/PE staining assay." (PMID 22984561, 2012).
medulloblastoma (continued). "We therefore examined the possible role of MMP-9 in the anti-angiogenic effect of SPARC-overexpressed Daoy medulloblastoma cells." (PMID 20087345, 2010). "We also analysed the effect of MMP-9 on the in vivo consequences of SPARC expression on medulloblastoma tumour formation in nude mice." (PMID 20087345, 2010). "Moreover, decreased expression of VEGF and MMP-9 in medulloblastoma cells overexpressing osteonectin resulted in decreased angiogenesis and tumor growth, indicating the pro-angiogenic role of MMP-9 in cancer tissues." (PMID 36674806, 2023). "Decreased expression of VEGF and MMP-9 in medulloblastoma cells that overexpress osteonectin, also referred to as Secreted Protein Acidic and Rich in Cysteine (SPARC), leads to decreased angiogenesis and tumor growth, indicating the pro-angiogenic role of MMP-9 in cancer tissues." (PMID 31921634, 2019). "Taken together, our results illustrated that RNAi mediated targeting of uPAR and MMP-9 might have therapeutic potential against medulloblastoma." (PMID 22984561, 2012). "Taken together, the data from the present study suggest that apoptosis induced in uPAR and MMP-9-downregulated medulloblastoma cells might be due to inactivation of the STAT3-related signaling pathway." (PMID 22984561, 2012). "In addition, treating pre-established medulloblastoma with siRNAs against uPAR and MMP-9 both alone or in combination with radiation suppressed uPAR, MMP-9, EGFR, STAT3 expression and induced Bak activation leading to apoptosis." (PMID 22984561, 2012). "In a medulloblastoma cell line, Rieken S el al. have recently demonstrated that heavy-ions could inhibit cell migration through downregulation of MMP-9 and upregulation of proadhesive cell surface integrin alpha-5 leading to increased cell adherence to extracellular matrix proteins." (PMID 27374096, 2016). "Therefore, by assessing the mitochondria-derived factors mediating the cell death process we successfully demonstrated that inhibition of uPAR and MMP-9 decreased the expression of Bcl-2 and Bcl-xL, activated Bid cleavage, and enhanced Bak expression in medulloblastoma cells." (PMID 22984561, 2012). "PELP1 knockdown in medulloblastoma cells results in downregulation of NF-κB, including TRAF1 and IL-8, and expression of ECM-related genes MMP7, MMP9, and MMP1465, the latter of which is upregulated by microglia in late-stage NDD development." (PMID 34772945, 2021). "Blocking EFGR significantly inhibited the uPAR and MMP-9 induced EGFR and STAT3 activation in medulloblastoma cells compared to the cells treated with the isotype IgG." (PMID 22984561, 2012). "Our further investigation showed that downregulation of uPAR and MMP-9 inhibited the transcriptional activity of STAT3 in regulating the expression of Bcl-2 and survivin in medulloblastoma." (PMID 22984561, 2012). "In medulloblastoma, the overexpression of SPARC can inhibit the angiogenesis in tumour by lowering the expression and secretion of VEGF and MMP-9." (PMID 22957090, 2012). "Furthermore, SPARC overexpression induced a decreased expression of MMP9 and an increase of TIMP3 in medulloblastoma tumor." (PMID 23935929, 2013).
thoracic aortic aneurysm (17 papers, 2006 to 2025). An aneurysm formed in the wall of the proximal portion of the descending aorta proceeding from the arch of the aorta. "Matrix metalloproteinases (MMPs), particularly MMP-2 and MMP-9, are activated and increased in expression in thoracic aortic aneurysm (TAA)." (PMID 38469141, 2024). "MMP-9 contributes to cardiovascular remodeling, and mmp9 deletion attenuated thoracic aortic aneurysm formation in mouse model." (PMID 32321550, 2020). "As far as the mean values of MMP-9 are concerned, these were higher in patients with chronic aortic dissection (group B) and lower in patients with thoracic aortic aneurysm (group C)." (PMID 19886986, 2009). "Aneurysmal arterial dilation may represent an extreme form of positive remodeling, with increased MMP9 expression detected in human thoracic aortic aneurysms." (PMID 40356625, 2025). "There is a differential expression with MMP-9 increased and TIMP-1 and -2 reduced in the most common forms of thoracic aortic aneurysms." (PMID 37175712, 2023). "In the aorta, aggrecan degradation is likely to be due to increase in the activity and expression of aortic MMP-2, MMP-9 and Calpain-1 with advancing age33–37, whilst increased ADAMTS levels promote thoracic aortic aneurysm progression." (PMID 29867203, 2018). "Elastin and collagen degradation in thoracic aortic aneurysms is mediated by MMPs, particularly the gelatinases, MMP-2 and MMP-9." (PMID 16722611, 2006). "These study findings suggest that the dysregulation of MMP‐2 and MMP‐9, two key enzymes involved in the degradation of the ECM within the aortic wall, may play a crucial role in the pathogenesis of thoracic aortic aneurysms and dissections." (PMID 40581980, 2025).
Allergy (16 papers, 2012 to 2026). An allergy is an immune response or reaction to substances that are usually not harmful. "Other eye diseases that have been found to cause elevated MMP-9 levels include infection, allergy, pterygium, and conjunctival chalazion." (PMID 39464763, 2024). "Children with higher value of Growth Arrest and DNA Damage Inducible-α (GADD45A) as well as the proteases MPO and MMP9 also had higher risk to develop allergy." (PMID 33722194, 2021). "MMPs, such as MMP-9, are implicated in several allergic diseases including AD, in which they may alter tissue repair in favor of skin rearrangement." (PMID 36012541, 2022). "In a patient with allergy and elevated tear MMP-9, preoperative qualitative IVCM scan of basal corneal epithelium showed bright microparticles compatible with polymorphonuclear granulocytes/lymphocytes (white arrows, scan depth ~ 50 μm)." (PMID 41485028, 2026). "Among tear fluid, the vast majority of pro-inflammatory cytokines (especially Th2 and Th17 cytokines) in perennial allergies and MMP-9 together with IgA in seasonal allergies were increased." (PMID 35935953, 2022). "In contrast, the unique genes in the OTM group included Ddit3, Il1r2, Mmp9, Stfa2, and Stfa3, with the distinguishing feature of ‘allergy’ and ‘endopeptidase regulation’, which revealed the activation of macrophages after OTM." (PMID 35185928, 2022). "This could explain why some patients had elevated MMP-9 during April and May when enrollment began but by the summer months of June and July their allergy season had passed and resulted in this extended duration of reduction in MMP-9." (PMID 39022763, 2024). "HVE inhibited the release of mediators involved in skin autoimmunity (IL-6 and IL-17C) and allergy (TSLP, IL-6, CCL26, and MMP-9) with a concentration-dependent fashion (IC50s < 25 μg/mL)." (PMID 36012541, 2022).
cholesteatoma (16 papers, 2007 to 2025). A pathologic process characterized by the proliferation of keratinizing squamous epithelium resulting in the accumulation of keratin and cells in the middle ear and/or mastoid. "Remodeling factors matrix metalloproteinase 2 and 9 (MMP-2 and MMP-9) can cause bone destruction in the case of cholesteatoma." (PMID 38535082, 2024). "The remodeling factors MMP-2 and MMP-9 are associated with bone remodulation in the middle ear for patients with cholesteatoma." (PMID 36837507, 2023). "Furthermore, IL-1α induces osteoclast function and increases bone matrix degradation, and it is known that MMP-2 and MMP-9 also cause bone matrix degradation for patients with cholesteatoma." (PMID 38535082, 2024). "Marimastat is a broad‐spectrum matrix inhibitor targeting matrix metalloproteinases (MMPs), including MMP‐2 and MMP‐9, demonstrating therapeutic potential for cholesteatoma‐related pathologies." (PMID 40837198, 2025). "MMP‐2 and MMP‐9 not only modulate inflammatory responses through pro‐inflammatory cytokine release in cholesteatoma microenvironments, but also have been characterized in histopathological specimens as a biomarker predictive of ossicular chain destruction." (PMID 40837198, 2025). "Limited data exist on the role of decreased levels of MMP-9 in cholesteatoma or any other pathology in humans." (PMID 36837507, 2023). "In an inflammatory environment, such as chronic otitis media with cholesteatoma, MMP-2 and MMP-9 cause pathologic bone degradation." (PMID 36837507, 2023). "MMP-9 in cholesteatoma tissue is explicitly seen in areas with inflammatory cell infiltration, and also is seen in basal and suprabasal levels of the matrix." (PMID 35655767, 2022). "A very strong correlation between MMP-9 and TIMP-4 suggests that TIMP-4 in cholesteatoma tissue intercorrelates to MMP-9." (PMID 35655767, 2022). "Remodeling factor MMP-9 varied from occasional to moderate immunoreactive cells in the cholesteatoma matrix, the same amount of MMP-9 immunoreactive epitheliocytes was seen in the control group." (PMID 35655767, 2022). "MMP-9 immunoreactive cells in the cholesteatoma perimatrix varied from occasional to a few to moderate." (PMID 35655767, 2022). "As it was expected from the bone destructive behavior of cholesteatoma, a significantly elevated expression of MMP9 was measured in cholesteatoma samples, the highest level was found in adult recurrent cases." (PMID 30021014, 2018). "Compared to the control sample, the expression of the MMP9 was significantly increased in the recurrent cholesteatoma group, the highest mRNA expression level was found in adult recurrent cases." (PMID 30021014, 2018). "Increased MMP9 production is consistent with the aggressive, destructive phenotype of cholesteatoma." (PMID 30021014, 2018). "Hierarchical clustering reveals that the mRNA profiles of control samples (EAS1-EAS7) differed in comparison to cholesteatoma samples (Chole1-Chole7) concerning the expression of inflammation-related genes such as metalloproteinases (e.g. MMP9)." (PMID 23285167, 2012). "MMP-2 and MMP-9 are not only found in OM with effusion but also in pediatric patients with cholesteatoma, a chronic stage of otitis media." (PMID 22655080, 2012). "Back in 1998, Banerjee, James and Narula demonstrated that MMP2 and MMP9 were present in cholesteatomas and in the external auditory canal skin." (PMID 17505599, 2007). "The intercorrelations we found among IL-1α and MMP-2 and MMP-9 may support the theory that MMP activity is also regulated by IL-1α in cholesteatoma tissue." (PMID 38535082, 2024). "We can speculate as to the specific decreased-expression pattern of MMPs in cholesteatoma soft tissue, but the lack of studies on this topic prevents us from expanding the role of decreased MMP-9 in cholesteatoma tissue." (PMID 36837507, 2023). "It was observed that MMP-9 and MMP-2 overexpression may be implicated in the molecular inflammatory pathways in cholesteatoma development." (PMID 37762439, 2023).